RORA (RAR related orphan receptor A)
Diseases named in the same sentence as RORA in open-access papers (continued):
Sharing a sentence is not in itself a finding about the gene and the disease.
Sepsis (continued). "Prior studies demonstrated that decreased RORα in ischemic and hypertrophic heart disease might compromise the effect of melatonin, while its role in the sepsis heart was unknown." (PMID 37147703, 2023). "This study dedicated to deciphering the mechanisms underlying the suboptimal benefits of melatonin in clinical trials confirmed that the nuclear receptor RORα-dependent signal was indispensable for the cardioprotection of a clinically safe dose of melatonin under lethal sepsis." (PMID 37147703, 2023). "Moreover, the broken and swollen myocardial fibers in fatal sepsis were largely lessened by melatonin and RORα delivery beyond melatonin monotherapy." (PMID 37147703, 2023). "Considering the biocompatibility, safety, and efficiency of UTMD technology, the synergistic therapy of melatonin treatment and RORα/CMBs may be a promising therapeutic pattern against sepsis-induced cardiomyopathy." (PMID 37147703, 2023). "RORα expression was reversely correlated with the degree of sepsis severity in the mRNA microarray." (PMID 37147703, 2023). "Thus, UTMD-mediated nuclear receptor RORα delivery enhanced melatonin-mediated cardiac protection against sepsis-induced cardiomyopathy." (PMID 37147703, 2023). "RORα/CMBs and regular dose of melatonin synergistic therapy effectively alleviated the myocardial oxidative stress and mitochondrial impairment induced by sepsis, and thus significantly improved the heart function and survival status." (PMID 37147703, 2023). "Thus, UTMD-mediated target delivery of gene may be a promising strategy to rescue RORα expression in the sepsis heart." (PMID 37147703, 2023). "However, only RORα moderately decreased in cardiomyocytes under sepsis stress." (PMID 37147703, 2023). "Analysis of immune cell infiltration revealed significant positive correlations between RORA and counts of CD4 + T, CD8 + T, and NK cells in sepsis." (PMID 42096424, 2026). "Aflatoxin B1 was identified as a prospective therapeutic agent for sepsis based on CHD3, L3MBTL2, PHC1, RANGAP1, and RORA." (PMID 40274894, 2025). "As expected, intravenous melatonin administration at a dose of 2.5 mg/kg/12 h weakly improved LVEF and LVFS in rats with sepsis, whereas UTMD-mediated cardiac RORα overexpression further enhanced the protective effect of melatonin on heart function." (PMID 37147703, 2023). "Ultimately, by taking the intersection of the results from the three machine learning methods, we identified six feature genes in sepsis: CD81, CLU, GLRX, CKAP4, DPEP2, and BCL11B; and seven feature genes in atrial fibrillation: LDHB, CD81, PFKFB2, CKAP4, CXCR4, DPEP2, and RORA." (PMID 41359645, 2025). "This study shows that hub genes (RORA, L3MBTL2, PHC1, RPA1, CHD3, and RANGAP1) may distinguish controls and diseases to facilitate diagnosis of sepsis." (PMID 40274894, 2025). "Melatonin treatment moderately decreased serum CK-MB and LDH in sepsis rats, while RORα delivery further limited CK-MB not LDH leak." (PMID 37147703, 2023). "In summary, our study found that nuclear receptor RORα but not traditional melatonin receptors MT1/2 significantly decreased in sepsis-induced cardiomyopathy." (PMID 37147703, 2023). "We found a decreased mRNA level in cardiac nuclear RORα but not RORβ/γ or MT1/MT2 in both sepsis models, which was further confirmed by western blotting and immunohistochemical assays." (PMID 37147703, 2023). "We further evaluated classic and non-classic melatonin receptors and found that the mRNA and protein expression of nuclear receptor RORα, rather than MT1/2, was significantly reduced in the sepsis model." (PMID 37147703, 2023). "We found that the cardiac expression of RORα, not MT1/2, significantly decreased in rats with lethal sepsis." (PMID 37147703, 2023). "We found decreased nuclear receptors RORα, not melatonin receptors MT1/2, under lethal sepsis that may weaken the potential benefits of a mild dose of melatonin treatment." (PMID 37147703, 2023).
Sepsis (continued). "Sepsis moderately decreased PUFAs contents compared to the control, while the lipid peroxidation metabolites in sepsis hearts, especially those derived from arachidonic acid (ARA) and linoleic acid (LA), were substantially counteracted by melatonin and RORα delivery, not melatonin alone." (PMID 37147703, 2023). "We confirmed that the RORα gene but not melatonin increased RORα expression (increased by 150%) in H9C2 cells, suggesting that melatonin use might not rescue the decrease in RORα under sepsis." (PMID 37147703, 2023).
breast tumor (8 papers, 2014 to 2024). "RORA is downregulated in breast tumors compared to healthy breast tissue, where the expression of RORA suppresses the malignant phenotype of breast cells." (PMID 35414788, 2022). "RORA has recently been indicated as a breast tumor suppressor, as well as having a role in keratinocyte differentiation." (PMID 24758699, 2014). "In detail, RORα suppressed breast tumor invasion by inducing SEMA3F expression." (PMID 38184549, 2024). "Moreover, an inverse correlation has been observed between the expression of EZH2 and RORa in breast tumor tissues and their normal counterparts, as the RORa protein expression was level very low in tumors exhibiting high levels of EZH2." (PMID 39769907, 2024). "Moreover, Xu and colleagues have demonstrated that RORα suppresses breast tumor proliferation and invasion." (PMID 27602774, 2016). "In contrast, CLOCK, NPAS2, CIART/CHRONO, BHLHE40, RORA, and RORC were significantly up-regulated in these breast tumors." (PMID 38319971, 2024). "This is consistent with the finding showing SEMA3F, a direct RORα target gene with a ROR element, suppresses breast tumor invasion." (PMID 28052040, 2017).
diabetic cardiomyopathy (8 papers, 2018 to 2025). Diabetic cardiomyopathy is a disorder of the heart muscle in people with diabetes. "Moreover, the nuclear melatonin receptor RORα is down-regulated in the diabetic heart, and its deficiency aggravates the diabetic cardiomyopathy and HF." (PMID 30037127, 2018). "Furthermore, in in vivo mouse models, reduced levels of RORα, followed by inhibition of the autophagy flux, have also been observed in subjects suffering from diabetic cardiomyopathy and in association with diastolic dysfunction and cardiac remodeling of diabetic hearts." (PMID 39518891, 2024). "Our study proposed RORα as a novel target against high glucose-induced cardiac fibroblasts proliferation, which is beneficial to clarify ideal therapeutic implication for diabetic cardiomyopathy." (PMID 39950114, 2025). "In vitro and in vivo studies illustrate that H2S can preserve mitochondrial function, reduce oxidative stress, and inhibit necroptosis in a RORα-dependent manner in patients suffering from diabetic cardiomyopathy." (PMID 39518891, 2024). "The cardioprotective function of RORα is also evident in patients suffering from diabetic cardiomyopathy, where overexpression of RORα reduces cell death mediated by autophagy dysfunction." (PMID 39518891, 2024). "In patients suffering from diabetic cardiomyopathy, RORα has been found to reduce oxidative stress, apoptosis, and autophagic dysfunction, thereby leading to the attenuation of disease progression and cardiac dysfunction." (PMID 39518891, 2024). "RORA is an endogenous protective receptor against diabetic cardiomyopathy by inhibiting oxidative stress and apoptosis in mouse models." (PMID 37542143, 2023). "Consistent with genetic manipulation, pharmacological activation of RORα by melatonin and SR1078 (a synthetic agonist) showed beneficial effects against diabetic cardiomyopathy, while the RORα inhibitor SR3335 significantly exacerbated cardiac impairments in diabetic mice." (PMID 36670468, 2023). "Collectively, these findings suggest that cardiac-targeted manipulation of nuclear melatonin receptor RORα may hold promise for delaying diabetic cardiomyopathy development." (PMID 36670468, 2023).
epilepsy (8 papers, 2013 to 2025). A brain disorder characterized by episodes of abnormally increased neuronal discharge resulting in transient episodes of sensory or motor neurological dysfunction, or psychic dysfunction. "In various animal models of epilepsy, the circadian oscillation and steady-state levels of circadian genes, including Bmal1, Clock, Per1, Rev-Erbα, and Rorα, have been found to be associated with epilepsy." (PMID 40217344, 2025). "Various circadian genes such as Clock, Bmal1, Per1, Rev-erbα, and Rorα are involved in the regulation of epilepsy." (PMID 36013397, 2022). "It is known that the epilepsy induced by pilocarpine reduces RORα mRNA and protein expression in the hippocampus of rats during the early post-SE phase." (PMID 30116220, 2018).
liver diseases (8 papers, 2012 to 2025). "In liver macrophages, MaR1 binds to RORα, demonstrating the crucial regulatory role of RORα in inflammatory processes in liver diseases such as NASH." (PMID 39518891, 2024). "Genes of inflammation and immunity (CD276, CDH6, GCKR, HNF1A, HPR, ITGA1, RORA, and STAT4) have been shown to be expressed in liver disease patients." (PMID 22530132, 2012).
Alzheimer disease (7 papers, 2011 to 2022). A progressive, neurodegenerative disease characterized by loss of function and death of nerve cells in several areas of the brain leading to loss of cognitive function such as memory and language. "As mitochondrial dysfunction is associated with various human diseases, including Alzheimer’s disease, multiple sclerosis (MS), and retinal diseases, the roles of RORα in the pathophysiology of these diseases should be addressed." (PMID 29167529, 2017). "RORα also potentially regulates transcription of brain-derived neurotrophic factor, which is associated with Alzheimer’s disease." (PMID 26383638, 2015). "Interestingly, ALG2 is among the top RAR-related orphan receptor A (RORA)-linked genes with elevated expression in the hippocampus of patients with Alzheimer’s disease." (PMID 31426446, 2019). "PPARGC1A and RORA are involved in circadian rhythm; circadian disturbances are one of the earliest symptoms of Alzheimer’s disease." (PMID 31283791, 2019). "In addition, previous studies have shown that the regular circadian rhythm of RORα was disturbed in Alzheimer’s Disease (AD) rat models." (PMID 35803929, 2022).
glioblastoma (7 papers, 2014 to 2025). The most malignant astrocytic tumor (WHO grade IV). "A recent study confirmed that EIF4A3 played a role in the EIF4A3/CASC2/RORA loop and ultimately facilitated the aggressive phenotype of glioblastoma." (PMID 35936722, 2022). "RORα expression was lower in HGG glioblastoma compared to LGG." (PMID 41425709, 2025). "RORα levels are higher in glioblastoma than in healthy controls." (PMID 41425709, 2025). "Moreover, we have certified that RORA mRNA and protein were also downregulated in glioblastoma." (PMID 34408982, 2021).
multiple sclerosis (7 papers, 2017 to 2024). A progressive autoimmune disorder affecting the central nervous system resulting in demyelination. "Multiple sclerosis progression is tamed by restraining Th17 cell differentiation and stimulating type 1 regulatory T (Tr1) cell differentiation via the melatonin-RORα axis." (PMID 34064466, 2021). "RORα gene expression is downregulated in the blood of multiple sclerosis patients." (PMID 35309302, 2022). "RORα, a member of the orphan nuclear receptor (ONR) family, plays a critical role in the regulation of inflammation during migraine, cancer, and multiple sclerosis." (PMID 38265549, 2024).
myocardial ischemia (7 papers, 2019 to 2025). A disorder of cardiac function caused by insufficient blood flow to the muscle tissue of the heart. "RORA deficient staggered mice subjected to myocardial ischemia/reperfusion injury show significantly increased myocardial infarct size, myocardial apoptosis, and exacerbated contractile dysfunction compared to wild-type mice." (PMID 33240937, 2020). "Our results agree with previous report that RORα deprivation results in autophagy dysfunction by interrupting autophagosome clearance in myocardial ischemia/reperfusion injury mice model." (PMID 30923260, 2019). "During myocardial ischemia/reperfusion injury, cellular autophagy levels are significantly inhibited, and the absence of RORA significantly exacerbates this autophagy inhibition, suggesting that endogenous RORA may help restore autophagy function after myocardial ischemia/reperfusion injury." (PMID 40001602, 2025).
colorectal cancer (6 papers, 2018 to 2025). A primary or metastatic malignant neoplasm that affects the colon or rectum. "RORα inhibited the proliferation and invasion of colorectal cancer cells in vitro and in vivo, and the growth and metastasis of transplanted tumors in nude mice, while the effect of RORα knockdown was contrary." (PMID 41425709, 2025).
endometrial cancer (6 papers, 2021 to 2025). Primary or metastatic malignant neoplasm involving the endometrium (mucous membrane that lines the endometrial cavity). "miR-652 can activate the Wnt/β-catenin signaling pathway to promote the proliferation and metastasis of endometrial cancer cells by directly targeting RORA." (PMID 35111226, 2022).
inflammatory bowel disease (6 papers, 2013 to 2023). A spectrum of small and large bowel inflammatory diseases of unknown etiology. "It was also demonstrated that RORα controls the inflammatory signaling network, which is implicated in inflammatory bowel disease (IBD)." (PMID 32610705, 2020). "KEGG pathway analysis indicated RORα was involved in regulation of cytokine–cytokine receptor interactions, inflammatory bowel disease, TNF signaling pathways, and Jak-STAT signaling pathways." (PMID 33397953, 2021). "The RORα/HDAC3-mediated attenuation of NF-κB signaling controls the balance of inflammatory responses, suggesting that therapeutic strategies targeting this epigenetic regulation may be beneficial in the treatment of chronic inflammatory diseases, including inflammatory bowel disease (IBD)." (PMID 34973135, 2023).
ovarian carcinoma (6 papers, 2019 to 2025). A malignant neoplasm originating from the surface ovarian epithelium. "Study proves that PS VII can induce apoptosis of drug-resistant ovarian cancer cells by up-regulating RORα and improve drug resistance therapy." (PMID 41425709, 2025). "Based on this, we confirmed once again in clinical samples that the RORα/ECM1/VEGFR2 signaling axis is closely associated with PARP inhibitor resistance, disease progression, and survival prognosis in ovarian cancer." (PMID 38725854, 2024). "RORα was significantly low expression in ovarian cancer tissue resistant to PARP inhibitors, while it was high expression in sensitive tissue." (PMID 38725854, 2024). "The inhibition of ECM1 expression was also observed to rescue cell migration and angiogenesis and to restore the glucose uptake and lactate, ATP, and NADPH efficacy of PS VII against PARP inhibitor-resistant ovarian cancer cells under RORα downregulation." (PMID 38725854, 2024). "To understand the signaling pathway of RORα in ovarian cancer cells, we performed RNA-seq analysis on cells with knocked-down or overexpressed RORα in PARP inhibitor-resistant cells." (PMID 38725854, 2024). "Next, we also examined the impact of PS VII on the migration and invasion phenotypes of ovarian cancer cells after downregulating RORα expression." (PMID 38725854, 2024). "LncRNA WDFY3-AS2 and mRNA RORA are both involved in suppression of ovarian cancer by the WDFY3-AS2/miR-18a/RORA axis, in which miR-18a is reported to be an oncogene." (PMID 35419410, 2022). "WDFY3-AS2 suppresses cell proliferation, migration, invasion, and epithelial-to-mesenchymal transition (EMT) via miR-18a/RORA axis in ovarian cancer." (PMID 34095147, 2021). "For instance, lncRNA WDFY3-AS2 can regulate the expression of RORA via sponging miR-18a in ovarian cancer." (PMID 31827399, 2019). "Further analysis of clinical data revealed that low expression of RORα and high expression of ECM1 and VEGFR2 were all associated with poor overall survival (OS) and progression-free survival (PFS) in patients with PARP inhibitor-resistant ovarian cancer." (PMID 38725854, 2024). "Its potential function may hinder glycolysis and angiogenesis in PARPi resistant ovarian cancer cells, which is associated with PS VII binding and stabilizing RORα expression, further inhibiting ECM1 and blocking the VEGFR2/FAK/AKT/GSK3β signaling pathway." (PMID 38725854, 2024). "Therefore, we believe that the RORα/ECM1 axis plays an important role in PS VII's treatment of PARP inhibitor-resistant ovarian cancer." (PMID 38725854, 2024). "We further investigated whether RORα regulates glycolysis and angiogenesis levels in ovarian cancer cells." (PMID 38725854, 2024). "It suggests that PS VII may serve as an RORα activator for targeted therapy in the clinical treatment of ovarian cancer." (PMID 38725854, 2024). "Moreover, we have discovered the specific mechanism by which PS VII reverses PARP inhibitor resistance in ovarian cancer through the RORα/ECM1/VEGFR2 signaling axis." (PMID 38725854, 2024). "In this study, we tested whether VDR, RORγ, and RORα are expressed in ovarian cancers, and we correlated their expression with clinico-pathological data, including patient survival time." (PMID 33227893, 2020). "Additionally, we found that PS VII potentially hindered glycolysis and angiogenesis in PARPi-resistant ovarian cancer cells by binding and stabilizing the expression of RORα, thus further inhibiting ECM1 and interfering with the VEGFR2/FAK/AKT/GSK3β signaling pathway." (PMID 38725854, 2024). "We found that the inhibitory effect of PS VII on the glycolysis level of ovarian cancer SKOV3 PARPi-R and HEY PARPi-R cells was reversed when RORα expression was downregulated." (PMID 38725854, 2024).